BRAF (B-Raf proto-oncogene, serine/threonine kinase)
Diseases named in the same sentence as BRAF in open-access papers (continued):
Sharing a sentence is not in itself a finding about the gene and the disease.
thyroid nodule (continued). "Moreover, in this study, all thyroid nodules harboring the BRAF V600E mutation were classified as Bethesda III." (PMID 39766147, 2024). "In conclusion, our results expand the spectrum of BRAF non-V600E mutations in thyroid nodules." (PMID 36835466, 2023). "In our series, K601E-mutant FV-PTC showed no aggressive features, such as extrathyroidal extension, vascular invasion, or metastases, supporting the notion that BRAF p.K601E mutated thyroid nodules are typically indolent, in contrast to BRAF p.V600E mutated carcinomas." (PMID 36835466, 2023). "Thus, CLNM was associated with age, maximum diameter of thyroid nodules, capsular invasion, and BRAF V600E gene mutation." (PMID 36750791, 2023). "Occurrence of macrocalcification in thyroid nodules may suggest a high risk of PTC, and the combination of US-FNAB and BRAF V600E showed a greater value in identifying macro-calcified thyroid nodules, especially with significantly higher sensitivity." (PMID 37194091, 2023). "And since macrocalcification often caused unsatisfied sampling, this progress may help BRAF V600E well complement with US-FNAB in evaluating macro-calcified thyroid nodules." (PMID 37194091, 2023). "Finally, our findings showed that the MS method was a precise and dependable alternative for detecting BRAF mutations in patients with thyroid nodules." (PMID 35992139, 2022). "However, basic research on thyroid nodules represents just a small portion of the medical literature on tumor markers such as BRAF (V600E) mutations, RET-PTC, and RAS, whose sensitivity and specificity are still insufficient." (PMID 36714145, 2022). "We attempted to develop a nomogram diagnostic model for BRAF mutations based on clinical and ultrasound features of patients to assist in the identification of benign and malignant thyroid nodules by FNA, thereby reducing clinical costs and improving diagnostic efficiency." (PMID 36160023, 2022). "Microcalcification was most commonly observed in malignant thyroid nodules and may be linked to BRAF gene mutations." (PMID 36160023, 2022). "Thus, this study was conducted to create a nomogram diagnostic model based on the clinical and ultrasonic characteristics of patients with BRAF mutations to aid in the identification of benign and malignant thyroid nodules using FNA." (PMID 36160023, 2022). "Although our study highlights the major clinico-pathological features of thyroid nodules with GEAs, further investigation is needed to characterize GEAs in isolation and in association with BRAF V600E in order to properly assess their diagnostic and prognostic utility." (PMID 36612045, 2022). "TIRADS classification and BRAF mutation status in 121 thyroid nodules with indeterminate cytology." (PMID 35047385, 2021). "However, it cannot be excluded that sporadically scattered malignant cells escaped microscopic observation although a recent meta-analysis reported some sporadic cases (1.2%) of indeterminate thyroid nodules with BRAF mutation associated with benign histology." (PMID 33716969, 2021). "BRAF V600E mutation is the most common mutation in these malignant thyroid nodules." (PMID 34322384, 2021). "Consequently, some authors recommend, that fine-needle aspiration should be routinely accompanied by the BRAF V600E mutation test in high-risk thyroid nodules with ≥2 suspicious ultrasound features." (PMID 34070605, 2021). "Interestingly, in our study, 2 out of 11 patients (18.2%) with benign nodular hyperplasia did have the BRAF (V600E) mutation in the index thyroid nodule FFPE samples." (PMID 34475951, 2021).
thyroid nodule (continued). "Additionally, in this study, over half of thyroid nodules were classified in category I (undiagnosed) and II (benign) and the BRAF V600E mutation rates were 12% and 4%, respectively, with similar malignancy rates reported in previous studies." (PMID 32671901, 2020). "One of the most widely used methods for BRAF V600E detection in thyroid nodules is PCR with amplification‐refractory mutation system (ARMS); this is a well‐established technique that has been widely used for rapid detection of nucleic acid mutations in a wide variety of biological samples." (PMID 32671901, 2020). "Therefore, in this study, we validated and compared the clinical utility of ddPCR to ARMS‐PCR for the detection of the BRAF V600E mutation in FNA specimens of thyroid nodules, using pathological diagnosis following surgery as the gold standard." (PMID 32671901, 2020). "Numerous studies have characterized indeterminate thyroid nodules by analyzing BRAF V600E mutation." (PMID 32976686, 2020). "Thus, for thyroid nodule patients, particularly the patients with indeterminate cytological findings, preoperative evaluation of a specific molecular marker, such as BRAF mutation, would be greatly helpful." (PMID 24588959, 2014). "In addition to routine cytological examination, a number of molecular markers play an important role in the diagnosis of thyroid nodules, such as BRAF and Ras mutations, and RET/PTC rearrangements." (PMID 24588959, 2014). "In summary, combined detection of BRAF mutation and methylation markers on FNABs may be a useful strategy in evaluation of thyroid nodules with indeterminate cytological findings." (PMID 24588959, 2014). "In this study, we tested the role of BRAF mutation in the diagnosis of malignant thyroid nodules." (PMID 24588959, 2014). "In addition, since BRAF sequencing is so far the best molecular test used in the preoperative assessment of thyroid nodules malignancy, we also built a model including BRAF mutational status." (PMID 22958914, 2012). "Because of the associations with BRAF V600E mutations, most clinicians will generally treat thyroid nodules with less common BRAF alterations similarly; however, this may pose a risk of overtreatment if these other nodule genotypes exhibit less aggressive behavior." (PMID 40075589, 2025). "Therefore, the targets widely recognized and recommended by scholars at home and abroad were selected to compose a 6-gene test panel for thyroid nodule diagnosis, including BRAF V600E mutation, TERT mutation, and gene fusions (CCDC6-RET, NCOA4-RET, ETV6-NTRK3, EML4-NTRK3, STRN-ALK, and PAX8/PPARG)." (PMID 40586006, 2025). "Consequently, characterizing the association between GEA and BRAF V600E mutations may be integral to refining the diagnosis, prognosis, and management of indeterminate thyroid nodules." (PMID 36612045, 2022). "Moreover, the BRAF V600E mutation test may be used to distinguish between benign and malignant thyroid nodules (Malignant thyroid nodules is mainly referring to PTC and mPTC in our study)." (PMID 34664843, 2021). "However, BRAF mutation analysis may give little additive value for the diagnosis of thyroid nodules that have suspicious MN or MN findings on preoperative US or FNAB." (PMID 26020381, 2015). "Therefore, several molecular tests for adjustment of cytological diagnosis of thyroid nodules have been proposed, which included panel of somatic mutations (e.g., BRAF and NRAS mutation and/or RET/PTC translocation) and immunocytochemistry tests based on gene expression signatures." (PMID 25972898, 2015). "We aimed to retrospectively evaluate the sensitivity and specificity of BRAF and RAS mutation analysis performed on fresh washout fluid samples obtained from fine-needle aspiration (FNA) of thyroid nodules, specifically in cases with indeterminate cytology." (PMID 41595518, 2026).
thyroid nodule (continued). "Our study demonstrated that BRAF and RAS mutation analysis performed on fresh FNA washout material is a feasible, accurate, and cost-effective adjunct for evaluating indeterminate thyroid nodules." (PMID 41595518, 2026). "In MPTC nodules, they found that 4 to 13% of patients with a BRAF V600E-positive thyroid nodule will recur." (PMID 40805249, 2025). "In the Bethesda IV group, two patients (2.8%, 2/72)—a 26-year-old man and a 50-year-old woman, both with BRAF V600E-negative thyroid nodules—developed new nodules one year and two years after ablation, respectively." (PMID 40385358, 2025). "Eligible studies involved individuals with AUS thyroid nodules, and the interventions under investigation were patients who received BRAF gene testing." (PMID 40970023, 2025). "The results of the 6-gene test panel (BRAF V600E, TERT mutations, and gene fusions) demonstrated excellent diagnostic performance with high specificity and PPV in diagnosing thyroid nodules." (PMID 40586006, 2025). "This prospective study aims to investigate the clinical applicability of the ThyroSCAN PanelChip, a qPCR-based method, for preoperative BRAF V600E testing in thyroid nodules." (PMID 40310607, 2025). "The integration of BRAF V600E mutation analysis with cytological evaluation and US-RSS enhances the diagnostic accuracy for AUS thyroid nodules." (PMID 40970023, 2025). "A subsequent prospective study (Testing3) involving 70 thyroid nodules further evaluated the model’s performance, where the selected optimal model was compared against FNAC combined with BRAF V600E mutation analysis." (PMID 40469435, 2025). "In the Bethesda III group, one patient (1.2%, 1/82), a 58-year-old woman with a BRAF V600E-negative thyroid nodule, developed a new nodule one year after ablation." (PMID 40385358, 2025). "It should be noted that fine needle aspiration biopsy of thyroid nodules should be performed before catheter drainage, and the benign and malignant nodules should be judged by cytopathology and BRAF gene detection." (PMID 40937415, 2025). "Molecular testing has gained prominence in diagnosing indeterminate thyroid nodules and two molecular profiles have been identified: BRAF V600E-like and RAS-like." (PMID 39568807, 2024). "We present a case featuring an indeterminate thyroid nodule whose FNA molecular testing showed BRAF V600E positivity, whereas, the final pathology surprisingly revealed a follicular carcinoma." (PMID 39288226, 2024). "In this study, we explored the clinical and histopathological characteristics of thyroid nodules with TERTp molecular alterations alone versus those with concurrent molecular alterations, particularly BRAF V600E and RAS." (PMID 39456540, 2024). "Our current study aimed to investigate the relationship between macrocalcification and PTC in thyroid nodules, and further explore the diagnostic efficiency of US-FNAB and BRAF V600E mutation in macro-calcified thyroid nodules evaluation." (PMID 37194091, 2023). "Preoperative FNA and BRAF gene testing benefit PTC diagnosis, and they are extensively used for risk stratification in patients with ultrasonographically suspicious malignant thyroid nodules." (PMID 38047112, 2023). "The aim of the present study was to report the experience of the Bologna molecular pathology laboratory regarding the frequency of BRAF non-V600E alterations in a large clinical cohort of thyroid nodules." (PMID 36835466, 2023). "In thyroid nodules with aggressive features, GEA was most commonly associated with BRAF V600E mutation (n = 18, 54.5%) and CNAs (n = 5, 15.2%)." (PMID 36612045, 2022). "TERT positive patients had the largest thyroid nodules of 16.2 (1.9–27.2) mL, fusions 3.8 (0.3–22.2) mL, and BRAF positive 2.3 (0.3–12.2) mL." (PMID 35625691, 2022).
thyroid nodule (continued). "In this study, the BRAF V600E testing results and the ultrasonographic appearance of the thyroid nodules were combined to increase the accuracy of PTMC diagnosis, allowing the invasiveness of nodules to be inferred." (PMID 35356255, 2022). "As a result, preliminary BRAF screening is required for all patients with thyroid nodules to aid clinical diagnosis." (PMID 35992139, 2022). "Patients with thyroid nodules (n = 186), for which BRAF V600E testing and cytopathology analysis were performed, and who underwent subsequent surgery for nodule resection were enrolled in this study." (PMID 35356255, 2022). "The predictive values of the BRAF V600E mutation test and TBSRTC categories were evaluated in these 131 thyroid nodules." (PMID 34664843, 2021). "This diagnostic study develops and tests a sensitive molecular assay for BRAF V600E variation detection in the remaining tissue from fine-needle aspiration biopsies of thyroid nodules." (PMID 34613404, 2021). "The objective of this study is to investigate the efficiencies of the v-raf murine sarcoma viral oncogene homolog B1 (BRAF) V600E mutation test and the TBSRTC categories in distinguishing between benign and malignant thyroid nodules." (PMID 34664843, 2021). "In spite of the limitations, this is the first study that compared the clinical validity of ddPCR to ARMS‐PCR in BRAF V600E detection on FNA specimens from thyroid nodules using the pathological diagnosis following surgery as the gold standard." (PMID 32671901, 2020). "This study aimed to investigate the diagnostic utility of BRAF, NRAS, and TERT promoter mutation in thyroid nodules at Dharmais Cancer Hospital." (PMID 33247684, 2020). "This study highlighted the superior performance of ddPCR over ARMS in BRAF V600E detection from thyroid nodule FNA samples." (PMID 32671901, 2020). "Taking these considerations into account, the utility of BRAF testing of thyroid nodules must therefore be explored in specific populations." (PMID 29808165, 2018). "A feasibility study was conducted by detecting BRAF(V600E) circulating tumour DNA (ctDNA) in the plasma of patients with thyroid nodules to distinguish between benign and malignant nodules." (PMID 29996517, 2018). "In our institution, we recommend surgery for BRAF or RAS-positive thyroid nodules with preoperative cytological diagnosis of AUS/FLUS and FN/SFN categories, and have been able to detect considerable numbers of PTCs in cytologically-indeterminate nodules." (PMID 28417935, 2017). "For example, total nomogram points for thyroid nodules with IR US, AUS/FLUS FNAB, and positive BRAF mutation were 105 [20 (IR US) + 20 (AUS/FLUS FNAB) + 65 (positive BRAF)] and the predicted probability of PTC was approximately 85% to 90%." (PMID 26020381, 2015). "By our nomogram, the probability of PTC for thyroid nodules with IR US, AUS/FLUS FNAB, and positive BRAF V600E mutation was approximately 85% to 90%." (PMID 26020381, 2015). "BRAF V600E detection is currently used as molecular test to improve the diagnosis of thyroid nodules, yet it lacks sensitivity." (PMID 26581891, 2015). "BRAF mutational analysis followed by N, H, and KRAS codon 61 mutational analysis in indeterminate thyroid nodules would streamline the management of patients with malignancies, mostly FVPTC." (PMID 25648502, 2015). "Nowadays, a number of molecular tests to confirm the diagnosis of thyroid nodules have been proposed, which included panel of somatic mutations (e.g., RET-PTC, RAS) and immunocytochemistry tests (e.g., BRAF V600E IHC)." (PMID 25972898, 2015). "Given that both of BRAF mutation and gene methylation play a key role in thyroid carcinogenesis and there is certain relationship between them, we presume that combined detection of these two molecular events on FNABs may improve the diagnostic accuracy of thyroid nodules." (PMID 24588959, 2014).
thyroid nodule (continued). "Subsequently, we performed BRAF mutation detection and Q-MSP assay on FNABs from 38 patients with thyroid nodules (defined as test group), with a blinded histologic diagnosis." (PMID 24588959, 2014). "We propose the use of BRAF test (after uncertain cytological diagnosis) to assess the malignancy of thyroid nodules at first, then the use of the c-KIT expression to ultimately assess the diagnosis of the nodules that otherwise would remain suspicious." (PMID 22233760, 2012). "Although this is the largest series, to our knowledge, of non-V600E BRAF mutant thyroid nodules with clinicopathologic correlation, further studies will help to better characterize these nodules, particularly those with less common genotypes (e.g., other than K601E)." (PMID 40075589, 2025). "The study concluded that combining cytomorphology-based subcategorization with BRAF V600E mutation testing provided critical insights for risk stratification and could enhance the preoperative diagnostic accuracy for AUS thyroid nodules." (PMID 40970023, 2025). "Discrimination of interpatient variabilities in RAS in combination with BRAF V600E and TERT promoter variants could facilitate cytology examinations in preoperative precision malignancy diagnosis among patients with thyroid nodules." (PMID 38758552, 2024). "We compared our molecular results with the histopathological outcomes, and we found that 7 patients out of a total of 22 patients that were surgically treated (due to the COVID-19 pandemic, only a few patients were able to be surgically treated) had positive BRAF malignant thyroid nodules." (PMID 39001288, 2024). "A total of 44 patients with BRAF V600E-positive thyroid nodules were included in this study." (PMID 38201541, 2023). "In conclusion, the evaluation of three miRNAs with recognized diagnostic potential for the differentiation of thyroid nodules, in combination with BRAF mutation and EU-TIRADS category assessment, supports clinical decision making in patients with thyroid nodules of category III." (PMID 37686562, 2023). "Fourth, our data showed that FNA and BRAF p.V600E genetic testing were selected according to doctors' experience, patients' wishes and medical expenses for thyroid nodule patients in the past 10 years, and these two examination methods may be overused." (PMID 36070149, 2023). "Besides, a total of 100 macro-calcified thyroid nodules with both results of US-FNAB and BRAF V600E mutation were screened out for subsequent evaluation of diagnostic efficiency." (PMID 37194091, 2023). "In addition, the diagnostic values of the BRAF V600E mutation test and thyroid FNA cytology alone and in combination the BRAF V600E mutation test and thyroid FNA cytology in distinguishing benign from malignant thyroid nodules were evaluated." (PMID 34664843, 2021). "Molecular markers, such as the BRAF V600E mutation or the TERT mutation, have been well studied in large cohorts, and the management of thyroid nodules harboring these mutations has also been recommended in the American and the European Thyroid Association Guidelines." (PMID 33923728, 2021). "Therefore, determining the molecular status of these thyroid nodules for the presence of BRAF V600E can help guide patient management." (PMID 34742355, 2021). "It has been speculated that these BRAF (V600E)-positive “benign” thyroid nodules may in fact be premalignant." (PMID 34475951, 2021). "The clinical utility of BRAF p.V600E is to improve diagnostic accuracy of fine-needle aspiration biopsy of indeterminate thyroid nodules, as the presence of BRAF p.V600E in the aspirate is almost synonymous with PTC with a high positive predictive value (95% to 100%)." (PMID 31835496, 2019).